IL2 (interleukin 2)
Diseases named in the same sentence as IL2 in open-access papers (continued):
Sharing a sentence is not in itself a finding about the gene and the disease.
tumor (continued). "SHP-1 deficient CAR19 T cells also secreted more IFNγ, TNFα, and IL-2 and these T cells were more efficient in killing tumor cells in vitro and in vivo." (PMID 33425916, 2020). "These approaches aim to increase anti-tumor efficacy and reduce IL-2-associated adverse effects by directed IL-2R binding, or targeting to the tumor site, and some of these molecules are currently in clinical trials." (PMID 33353953, 2020). "IL-10 is secreted in the TME and it has been shown to induce an exhausted phenotype on tumor infiltrating T cells characterized by low proliferation and suppressed secretion of cytokines associated with an effector phenotype as IL-2, IFNγ and TNFα." (PMID 32937953, 2020). "While T-bet ablation restricted the production of IFN-γ, loss of Blimp-1 prevented GzmB expression in response to IL-2, suggesting that two independent programmes required for the polyfunctionality of tumour-reactive cytotoxic CD4+ T cells." (PMID 32680511, 2020). "Several studies have shown that the expression level of CXCR3 and its ligands was significantly elevated in systemic high-dose interleukin-2 (IL-2) therapy, which suggests the promotion of tumor-specific immunity and association with prognosis." (PMID 32089645, 2020). "The cytotoxic CD8+ T cell population, supported by CD4+ T helper (Th1) cells through the production of IL2 and IFNγ, generates the final effector mechanism leading to tumor elimination and are associated with a good prognosis." (PMID 32423420, 2020). "While T-bet ablation restricted interferon-γ (IFN-γ) production, loss of Blimp-1 prevented GzmB expression in response to IL-2, suggesting two independent programs required for polyfunctionality of tumor-reactive CD4+ T cells." (PMID 31924474, 2020). "Whereas some tumor cell lines transfected with NCAM-140 showed enhanced susceptibility for the cytotoxicity of IL-2-activated NK cells (i.e., PANC-1, T98G), it reduced NK cell-mediated lysis in others (i.e., LP-1, SHEP, and RPMI-8226)." (PMID 31336622, 2019). "Three iv injections of ex vivo TKD/IL-2-activated NK cells, or 4 ip injections of mouse anti-PD-1 antibody caused a significant tumor growth delay." (PMID 30967859, 2019). "We first assessed the association between IL-2 expression in the tumor and the clinical outcome using TIMER website analysis." (PMID 31462678, 2019). "Anti-tumor: NCR+ILC3s produce IL-22, TNFα, IL-8 and IL-2 to activate endothelial cells forming protective tumor-associated tertiary lymphoid structures." (PMID 32117199, 2019). "PET tracers based on uncomplexed IL-2 and a tumor-targeted IL-2 variant have already been developed." (PMID 30808414, 2019). "These include tumor-targeted variants; another strategy is to avoid the binding of IL-2 to CD25 either by mutation or by complex formation with anti-IL-2 antibodies such as the S4B6 monoclonal antibody." (PMID 30808414, 2019). "Even if the systemic delivery of IL-2 can be toxic, new manners to get IL-2 into a tumor have been evaluated (i.e., IL-2 encoded by an oncolytic virus or linked to a tumor-associated ligand)." (PMID 31500315, 2019). "RCC is recognized as a tumor that is susceptible to immunotherapy, including IL-2 and recombinant IFN-α." (PMID 31005126, 2019). "In the CD47−/− 3BD9 tumor microenvironment, there was a substantial increase in IL-2 and IFN-γ, the cytokines primarily associated with T cell health and deemed indispensable for T-reg cell activity and induction." (PMID 31882679, 2019). "In our study, the IL2 rs2069762 GG genotype was associated with lower oral cavity risk, in contrast to previous reported associations in another tumour types with different risk factors and ethnic background." (PMID 30959967, 2019). "Accordingly, combinations of tumor immunotherapeutics such as immune checkpoint blockers (ICBs), IL-2, IL-2 variants, or others, with immunogenic RT can be synergistic." (PMID 30808414, 2019).
tumor (continued). "To overcome these defects, we designed a next-generation IL-2 comprising a tumor-targeting antibody and a mutated human IL-2 that exhibits reduced CD25 binding and enhanced CD122 binding." (PMID 31462678, 2019). "Chronic inflammation has been confirmed to be strongly associated with tumor invasion, migration and metastasis through increased secretion of pro-inflammatory cytokines, such as IL-2, IL-6, tumor necrosis factor-α and so forth." (PMID 30513726, 2018). "A rather dominant effect of enterotoxins on MDSC-inducing signals has been shown in our co-culture experiments with tumor-associated GM-CSF, IL-2, and Pseudomonas- and Aspergillus- derived MDSC-inducing molecules." (PMID 30271756, 2018). "IL-2 is used systemically for cancer therapy and is associated with severe toxicity, whereas its effect is best kept within the tumour microenvironment." (PMID 30410056, 2018). "Macrophages from elderly mice impaired anti-tumor T cell function and was associated with poorer responses to IL-2/anti-CD40 immunotherapy." (PMID 30459812, 2018). "Monoclonal antibodies directed against TNF-α, VEGF, and IL-6 has shown promising results to ameliorate inflammation and cancer, while direct administration of IL-2 has been shown to cause tumor regression." (PMID 29662489, 2018). "T cell-rich tumors correlated with delayed recurrence or death and were associated with increased expression of Interleukin-2 (IL-2), IFNγ and lymphocyte-attracting chemokines within the tumor such as CXCL9, CCL21, and CCL22." (PMID 30042343, 2018). "Curiously, the infiltration of cytotoxic T lymphocytes is associated with the production of interferon γ (IFγ) and interleukin-2 (IL-2), which is associated with inhibition of tumor growth." (PMID 30545144, 2018). "The only common effect of IL-2/CD40 on tumor-associated CD11c+ cells seen in both age groups was up-regulation of IFN-γ." (PMID 30560130, 2018). "Unexpectedly, IL-2/CD40 promoted a more regulatory phenotype in young tumor-associated CD8+ T cells, on account of increases in several regulatory markers, relative to PBS controls, specifically: CD39, A2AR, A2BR, ICOS, LAG-3, and PD-1." (PMID 30560130, 2018). "The panel generally agreed that new lesions or an increase in tumor burden in patients treated with interferon or IL-2 is cause for treatment cessation." (PMID 29848375, 2018). "IL-2/CD40 induced several age-specific changes on tumor-associated CD11c+ cells including increased TGF-β on elderly DCs." (PMID 30560130, 2018). "Previous studies have implicated several cytokines, including IFNɤ, TNFα, and IL-2, as possible regulators of PD-L1 expression on the surface of several tumor cells, and IFNɤ has been thought as a strong inducer of PD-L1 expression in cancer cells." (PMID 30400941, 2018). "Tumor endothelium specific targeting was achieved by coupling IL2 to the small immune protein L19 that recognizes the extra domain B (ED-B) of fibronectin associated with tumor neovasculature." (PMID 30250827, 2018). "Caveats of systemic IL-2 administration include treatment-associated toxicity, its rapid clearance in vivo and IL-2 pro-tumor effects through the concurrent activation of CD4+ regulatory T cells." (PMID 29181007, 2017). "In another study, a tumor-targeted replication-competent virus (oncolytic virus) carrying the genes encoding for IL-2 and TNF-α, was used for IL-2 delivery to the tumor site." (PMID 28927416, 2017). "Surprisingly, however, such variants are less effective than wild-type IL-2-Fc in mediating tumour rejection." (PMID 28497796, 2017). "Flow cytometry revealed reduced Gzm-B substrate cleavage in mTORC1-inhibited (rapamycin-treated) IL-2 effectors, confirming a critical role for mTORC1 in regulating Gzm-B susceptibility of T-cell effectors within the tumor microenvironment." (PMID 28496990, 2017).
tumor (continued). "Here, the authors develop a long-lived variant of IL-2 that, mutated in its binding domain, drives a much more potent tumour regression by depleting CD25+ CD4+ regulatory T-cells via targeting them for phagocytosis." (PMID 28497796, 2017). "Since treatment efficacy is mediated by CD8+ and NK cell activity at the tumour site, considerable efforts have focused on generating variants that expand these subsets systemically, as exemplified by IL-2/antibody complexes and ‘superkines'." (PMID 28497796, 2017). "Renca tumor irradiation combined with intratumoral IL-2 cytokine adenovector gene therapy caused increased tumor destruction and infiltration of immune cells resulting in complete responses in 40–90% of the mice." (PMID 28116088, 2017). "IL-2, a hallmark of proinflammatory polarization, demonstrated a robust tumor x treatment interaction." (PMID 27893434, 2017). "The levels of CD4+Foxp3+ cells had a negative impact on adoptive immunotherapy and immune responses that is consistent with the increased anti-tumor effect of CAR-T with deleted lck domain of CD28 linked to IL-2 production." (PMID 26999211, 2016). "Future work will focus on tumour models containing tumour-associated antigens in order to study the interplay of the innate and adaptive immune system after targeted delivery of IL-2." (PMID 27650575, 2016). "The analysis of WASp KO NK cells implies that increased expression of KLRG1, LAG-3 and DNAM-1 was associated with normal tumor rejection capacity, at least when multiple ligands and cytokines such as IL-2 was produced by tumor cells." (PMID 27477778, 2016). "As it has been established, functional activity of T-cells and macrophages that reduces with age, bringing down antiviral, antibacterial and anti-tumor defense of the body, is directly associated with considerably reduced production of IL-2." (PMID 27574962, 2016). "Adoptive T cell transfer (ACT) using tumor-specific CD8+ T-cells are selected with specific tumor-associated antigens, expanded and activated with cytokines including interleukin (IL)-2, -7 and -15, then transfused back to the patient." (PMID 26683520, 2015). "There is great interest in the results of the ongoing SELECT trial, which is evaluating the tumor-associated predictors of responsiveness to IL-2." (PMID 26557408, 2015). "In the C3-B mouse model, the expression of the anticancer-associated cytokines (TNF-α, IFN-γ, IL-2, and IL-12) were measured by ELISA assay in the host spleen and the local tumor area." (PMID 25510204, 2014). "In human colon cancer cells, TIMP-1 conferred resistance against cytotoxicity caused by TNF-α and IL-2, and contributed to clonogenicity and tumor growth during early tumor formation." (PMID 24518611, 2014). "In contrast to the other NCR, NKp44 is not expressed on resting human NK cells but it is up-regulated on their surface after IL-2 stimulation and upon engagement mediates the killing of susceptible tumor cell lines." (PMID 24744763, 2014). "In clinical trials where γδTc were repetitively activated with n-BP or PAg together with low-dose IL-2, effects on tumor growth were observed; however, this was associated with exhaustion, anergy, or depletion of γδTc due to repetitive stimulation." (PMID 25566256, 2014). "Arming of recombinant H-1PV with these novel IL-2 variants or supplementing H-1PV-based virotherapy with IL-2 ‘superkine’ is worth considering to improve the efficiency of tumor therapy." (PMID 23902851, 2013). "Researchers have recently shown that mice treated with vector constructs that were able to encode for interleukin-2 (IL-2), IL-4, or IL-12 cytokines presented a rapid and sustained tumor regression." (PMID 23443138, 2013). "This was associated with increased tumor uptake of the antibody F8 (which selectively recognize perivascular EDA-fibronectin) conjugated to interleukin 2 (F8-IL2)." (PMID 24102047, 2013).
tumor (continued). "More importantly, treatment with the DNA construct encoding NKG2D-Fc-IL2 significantly enhanced the therapeutic anti-tumor effects generated by intradermal vaccination with therapeutic HPV DNA in tumor-bearing mice." (PMID 22509395, 2012). "To date, the majority of clinical progress has been made with ICs that have linked human interleukin-2 (IL2) to a select number of tumor reactive mAbs that had already been in prior clinical testing as non-modified mAbs." (PMID 24634778, 2012). "Although MHCII−/− mice with transferred polyclonal CD4+ T cells developed tumors, they had very low tumor burdens compared to mice receiving CD154-deficient or IL-2-deficient polyclonal CD4+ T cells." (PMID 23071696, 2012). "Low dose (5 mg/kg) entinostat reduced Foxp3 levels in Tregs and this was associated with enhanced tumor growth inhibition in combination with either IL-2 or a SurVaxM vaccine." (PMID 22303460, 2012). "Taken together, our data show that TC-1 tumor-bearing mice injected with the DNA construct encoding NKG2D-Fc-IL2 are capable of delivering IL-2 to the tumor loci, resulting in local proliferation and accumulation of E7-specific CD8+ T cells." (PMID 22509395, 2012). "Because NKG2D ligands have been shown to be highly expressed in many cancer cells but not in healthy cells, we reason that a chimeric protein consisting of NKG2D linked to IL-2 will lead to the specific targeting of IL-2 to the tumor location." (PMID 22509395, 2012). "In contrast, IFN-γ, TNF-α, IL-5, IL-4, IL-2 and low amounts of IL-10 were produced upon stimulation with the tumor cell lines encoding the HPV16E7wt and HPV16E7V constructs." (PMID 21892941, 2011). "The therapeutic potential of this approach has been demonstrated using a fusion construct encoding the anti-GD2 ganglioside binding site and IL-2 against a human neuroblastoma tumor in a SCID mouse model." (PMID 24213115, 2011). "In models of melanoma and renal cell carcinoma, administration of a high dose IL-2 based immunotherapy correlates with an elevated T regulatory (Treg) cell response associated with down regulation of tumor specific immunity." (PMID 20184734, 2010). "Culturing immune cells isolated from a cancer patient's peripheral blood, or excised tumor tissue, with IL-2 causes them to differentiate into LAK cells." (PMID 21253521, 2010). "This shift is characterized by increased protein expression of IL-2 and IL-7, suppressed recruitment of tumor-associated macrophages, myeloid derived suppressor cells, T regulatory cells, and decreased tumor angiogenesis and lymphangiogenesis." (PMID 19956757, 2009). "Although the combination of recombinant IL-2 and IL-12 treatment has been reported to be synergistic for inducing anti-tumor responses, systemic administration of these cytokines causes toxic side effects." (PMID 15485577, 2004). "IL-2 is also released by tumour infiltrating lymphocytes (TILs) and IL-6 is released by tumour associated macrophages (TAMs), TILs and fibroblasts." (PMID 15272933, 2004). "We have previously shown that an adenovirus vector expressing human IL-2 causes complete tumour regression in approximately 20–40% of the cases, whereas a simultaneous expression of B7-1 and IL-2 in a single vector have a much higher success rate, >90%." (PMID 12865933, 2003). "When ECT was associated with a local interleukin 2-based immunotherapy, increased local anti-tumour effectiveness as well as a large decrease in the number of metastases were observed." (PMID 9649121, 1998). "During both rounds of therapy different doses of L-NAME alone caused a reduction of primary tumour growth as well as spontaneous lung metastases, which improved further with the addition of IL-2." (PMID 8546905, 1996). "We further show the functionality of the LPS-freeOMV through the incorporation of an IL-2 variant protein (Neo-2/15).This functionalization augments OMV’s ability of the OMV toinhibit tumor growth and promote lymphocyte infiltration into thetumor microenvironment." (PMID 39763210, 2025).
tumor (continued). "However, there is very little information available about combination regimens using a Vaccinia virus strain expressing IL2 together with epitopes of tumor-associated antigens (TAAs) for cancer treatment." (PMID 41050655, 2025). "Furthermore, the combination approach triggered delayed hypersensitivity reactions, which were associated with enhanced activation of lymphocytes and tumor cell destruction, highlighting the synergistic benefits of liposomal IL-2 in cancer immunotherapy." (PMID 40143046, 2025). "Also, compared to IL-2 alone, the combination of IL-2 with gp100 (a tumor-associated antigen) showed significant improvement and progression-free survival." (PMID 40584631, 2025). "For example, human-IL-2 linked to tumor-reactive mAbs such as hu14.18-IL-2, anti-CD20-IL-2, DI-Leu16-IL-2, and anti-CEA M5A-IL-2 have shown similar trends of stimulating an antibody-directed response against cancer, including testing for cancer therapy currently in clinical trials." (PMID 40361381, 2025). "Although we have demonstrated the tumor therapeutic efficacy of VACV strains co-expressing IL2 with tumor-associated antigen epitopes in a mouse model—offering a promising strategy for oncolytic cancer immunotherapy—the translation of this concept into human clinical trials remains challenging." (PMID 41050655, 2025). "The increase of NK and NKT cells observed may be linked to locally augmented IL2 levels in tumor tissue." (PMID 40397803, 2025). "A study suggests that combining IL-2 with Tebentafusp might reduce tumor macrophage-caused suppression and assist in treatment outcomes in cases with high TAM-to-T cell ratios." (PMID 40564107, 2025). "Moreover, RT was combined with IL-2 variants that preferentially targeted effector immune cells or antigens present in the tumor microenvironment." (PMID 40502703, 2025). "However, despite the positive results, it was noted that a large number of patients experienced toxicities associated with the high doses of IL-2 required to achieve an effective anti-tumor response." (PMID 39091493, 2024). "Additionally, low-risk patients exhibited increased expression levels of most HLA genes, interleukin-2 (IL-2), and heightened activity in the M2-like tumor-associated macrophages (TAMs) pathway, as well as an elevated gene expression profile (GEP) score." (PMID 39569192, 2024). "Since bryostatin-1 broadly activates T cells in the presence of costimulatory signals or cytokines like IL-2, it may suggest a risk of triggering auto-reactive response while exerting its beneficial anti-tumor effects." (PMID 39877358, 2024). "The lactylation of Ikaros family zinc finger 1 (IKZF1) at lysine 164, for example, enhances the differentiation of Th17 cells by upregulating the expression of Th17-associated genes, including Runx1, Tlr4, IL-2, and IL-4, further contributing to the suppression of anti-tumor immunity." (PMID 39766353, 2024). "For example, IL-2 is conjugated to an antibody or antibody components, which could bind tumor-associated antigens (TAAs)." (PMID 38337114, 2024). "Tumor cell killing is associated with increased IL-2, TNF-α and/or IFN-γ secretion." (PMID 38582787, 2024). "In addition, another strategy to increase the immunogenicity of tumor cells is encoding cytokine genes (e.g., IL-2) on the same construct to attract T and NK cells capable of eliminating the tumor." (PMID 39340000, 2024). "IL-2 levels have been associated with better survival after ICIs in other tumor subtypes." (PMID 38799450, 2024). "We therefore tested whether PGE2 controls the IL-2-mediated expansion of TCF1+ TILs sorted from PGE2-deficient Ptgs1/Ptgs2−/− tumours (identified as TIM-3−CXCR6− TILs)." (PMID 38658748, 2024). "Consequently, the combined application of tumor immunotherapeutics, including ICBs, IL-2, IL-2 variants, and others, with immunogenic RT, promises synergistic potential." (PMID 39218928, 2024).